PIEZO1 (piezo type mechanosensitive ion channel component 1 (Er blood group))
Diseases named in the same sentence as PIEZO1 in open-access papers (continued):
Sharing a sentence is not in itself a finding about the gene and the disease.
tumor (continued). "Two weeks later, the fluorescence signals of tumor cells in mice were tracked using a bioluminescence imaging system, and the results showed that there were less tumor signals in Piezo1-silenced tumor cells." (PMID 36112948, 2022). "Collectively, these data suggest that Piezo1 suppresses the expression of growth inhibition factors and growth inhibitory signals in tumor cells." (PMID 36230880, 2022). "In conclusion, Piezo1 is overexpressed in OC tissues and contributes to OC tumor growth and metastasis." (PMID 35942515, 2022). "The tumor-immunomodulatory effects of Piezo1 on macrophages, DCs, and T cells are an area worthy of further investigation for the treatment of immune cell antitumor therapy." (PMID 36615408, 2022). "US irradiation simulates pressure changes in the tumor microenvironment and the instantaneous cation channel Piezo1 is observed to open, resulting in an influx of Ca2+." (PMID 35454942, 2022). "Piezo1 knockdown decreased the tumor growth rate of OC tumor xenografts in mice and reduced cell migration in vitro." (PMID 35942515, 2022). "Piezo1 can induce tumor angiogenesis by sensing mechanical forces and transmitting downstream signals." (PMID 36230880, 2022). "We evaluated Piezo1 in tumor tissues and adjacent tissues of OC patients by RT-PCR, western blot, and immunohistochemical analysis." (PMID 35942515, 2022). "To further confirm the influence of Piezo1 on the tumor cell metastasis ability, we applied the transendothelial migration assay in vitro." (PMID 36112948, 2022). "In turn, the firmer mechanical microenvironment boosts PIEZO1 expression and promotes tumor cell proliferation in a sort of auto-catalytic process." (PMID 35942524, 2022). "Based on the results obtained from in vitro experiments, we verified the role of Piezo1 in vascular extravasation of tumor cells in vivo using the lung metastasis mouse model." (PMID 36112948, 2022). "Mechanoptosis is driven by calcium entry through mechanosensitive Piezo1 channels that activate a calcium-induced calpain response commonly found in tumor cells." (PMID 36299893, 2022). "Recent evidence shows that fluid shear stress enhances the sensitivity of suspended tumor cells to TRAIL-mediated apoptosis via Piezo1-mediated Ca2+ influx and activation of calpains." (PMID 35510498, 2022). "In pancreatic ductal adenocarcinoma (PDA), the Piezo1 channel has been detected in myeloid cells as a sensor for mechanical stimulation in tumor cells." (PMID 36615408, 2022). "In this review, we present recent discoveries related to the role of the mechanosensitive ion channel Piezo1 in several diseases, especially in regulating tumor progression, and how this can be compared with cardiac mechanobiology." (PMID 35897650, 2022). "Together, these studies indicate that Piezo1 plays an important role in regulating the activation of proliferative signals that lead to excessive tumor cell proliferation." (PMID 36230880, 2022). "(A) MC38 tumor cells were implanted subcutaneously in WT and Piezo1-/- mice (n=10) and tumor size was measured every 5 days for 40 days." (PMID 35993548, 2022). "For instance, downregulating the expression of Piezo1 lowered intracellular Ca2+ levels in esophageal squamous cell carcinoma and then repressed tumor cell migration and invasion through the epithelial–mesenchymal transition pathway." (PMID 35701561, 2022). "Our results showed that PIEZO1 can be used to predict prognosis of different cancers, and it affected tumor infiltrating immune cells, which rises a pivotal role in tumor immunity." (PMID 35747124, 2022). "Cancer cells detect mechanostimulatory signals, transmuted into the cellular response by means of the mechanosensitive ion channel Piezo1, involved in mediating the infiltration of tumor cell Ca2+ into the cells." (PMID 36615408, 2022). "Recent studies showed that Piezo1 mediates tumor development through multiple mechanisms, and its overexpression is associated with poor prognosis." (PMID 36230880, 2022).
tumor (continued). "Piezo1 also promotes tumor cells’ invasiveness through a reciprocal regulation with matrix stiffness." (PMID 36230880, 2022). "Here we found that significant upregulation of Piezo1, a sensor of the mechanical microenvironment of the tumor, was observed in tumor tissue compared to normal tissues, which was associated with a poor prognosis in patients with OC." (PMID 35942515, 2022). "We performed in‐house PIEZO1 IHC analysis of 56 pairs of ESCC patients' tumor and paracancerous tissues as well as two tissue arrays including 162 ESCC patients' tumors and 66 corresponding normal tissues." (PMID 35608274, 2022). "Previous studies reported that tumor tissue stiffness provides a mechanical microenvironment to activate Piezo1." (PMID 36112948, 2022). "Further, similar expression levels of Piezo1 are observed in many matched pairs of tumor and normal cells, but it serves different roles in the tumor and normal cells." (PMID 34589605, 2021). "In the si‐Piezo1 group, the tumour cells had a loose structure, light nuclear staining, nuclear pyknosis in some cells and were scattered." (PMID 33439514, 2021). "The localization of Piezo1 to the periphery of tumor cells after US treatment correlated with an increase in the calcium entry." (PMID 34589605, 2021). "In the future, it will be important to determine the role of mechanical sensor Piezo1 in immune cell polarization and tumor immunity in cancer microenvironment." (PMID 34112781, 2021). "Haematoxylin & eosin (H&E) staining results showed that the tumour area in the si‐Piezo1 group was significantly decreased than that in the control group." (PMID 33439514, 2021). "Our animal experiments showed that inhibition of Piezo1 can prevent the tumour growth in omentum and peritoneal implantation." (PMID 33439514, 2021). "si‐Piezo1 significantly reduced collagen fibre and reticular fibre formation in peritoneal metastatic tumour tissues." (PMID 33439514, 2021). "Compared with the control group, the number and volume of tumour nodules on the omentum of nude mice in the si‐Piezo1 group were significantly reduced." (PMID 33439514, 2021). "Patients with tumours expressing PIEZO1 at high levels generally had a significantly shorter OS than those with lower expression." (PMID 32999349, 2020). "Given that both Piezo1 and Piezo2 are upregulated in specific cancer cells and tissues, their potential use as tumor biomarkers for diagnosis and prognosis is indisputable." (PMID 32635333, 2020). "To get a better understanding of how PSC physiology is affected in the acidic tumor core, we inspected how changes in intra- and extracellular pH affect Piezo1-elicited responses of PSCs." (PMID 32116794, 2020). "In NSCLC, knocking down both Piezo1 and Piezo2 by shRNA enhanced in vitro migratory capability and in vivo tumor growth." (PMID 32635333, 2020). "Taken together, PIEZO1 not only regulates tumour cell proliferation but modulates the TME as well to promote tumour cell metastasis." (PMID 32999349, 2020). "Because PIEZO1 plays a vital role in an abundance of physiological processes, more research needs to be done to investigate tumour-specific PIEZO1 knockdown and provide a potential tumour cell and TME-targeted therapy." (PMID 32999349, 2020). "To check the role of PIEZOs in tumor growth, we inoculated A549 cells with stable transfection of Veh sh-RNA, sh-PIEZO1, or sh-PIEZO2 into nude mice." (PMID 30745454, 2019). "The predicted roles of PIEZOs in NSCLC patients, both PIEZO1 and 2, are those involved in the suppression of tumor progression." (PMID 30745454, 2019). "Consequently, research is gradually shifting towards targeting Piezo1-mediated regulation of the tumour microenvironment, particularly the tumour immune microenvironment, rather than focusing solely on tumour cells." (PMID 41437911, 2026).
tumor (continued). "Such mechanically heterogeneous niches could dampen Piezo1 signaling in infiltrating NK cells, creating sanctuaries for tumor survival and thereby constituting a form of adaptive resistance to mechanical immunotherapy." (PMID 41607548, 2026). "The idea that temporally precise modulation of Piezo1 activity could be used to overcome fibrotic or stiffened tumor microenvironments is theoretically attractive but experimentally untested." (PMID 41607548, 2026). "However, within the TME, Piezo1 inhibition enhances the mechanical cytotoxicity of T cells against tumour cells." (PMID 41437911, 2026). "This creates a therapeutic paradox: a systemic Piezo1 agonist intended to boost NK cell function could simultaneously accelerate tumor progression." (PMID 41607548, 2026). "Understanding Piezo1 in this framework is crucial for developing novel therapies targeting tumour immune evasion, positioning Piezo1 as a tunable signalling hub rather than a simple mechanosensor and guiding the design of more precise immunomodulatory strategies." (PMID 41437911, 2026). "Piezo1 also plays crucial roles in various pathological processes, including the modulation of inflammatory responses through cytokine release and the promotion of cancer progression by facilitating tumour cell invasion, metastasis and angiogenesis." (PMID 41437911, 2026). "Piezo1 regulates ECM remodelling to promote tumour cell invasion." (PMID 41437911, 2026). "Conceptually, the integration of rationally designed Piezo1 modulation with Chimeric Antigen Receptor Natural Killer Cell Therapy (CAR-NK) holds potential to mitigate on-target off-tumor toxicities such as neurotoxicity by precisely fine-tuning NK cell activation thresholds." (PMID 41607548, 2026). "Future studies integrating single-cell sequencing and in vivo imaging to characterize the dynamic role of Piezo1 in tumour vasculature may provide new avenues for developing Piezo1-targeted immunotherapies." (PMID 41437911, 2026). "Consequently, the elevated interstitial pressure prevalent in tumour tissues persistently activates Piezo1, leading to pathological angiogenesis characterized by vessel tortuosity and leakage, which in turn facilitates tumour cell invasion and migration." (PMID 41437911, 2026). "Therefore, this review aims to systematically elucidate how mechanical stress regulates the NK cells’ function in tumor suppression through the core hub of Piezo1, and uncover the intricate molecular mechanisms involved in this process." (PMID 41607548, 2026). "Targeting the Piezo1 pathway or reducing ECM stiffness may provide promising therapeutic strategies to overcome tumour-induced immune inhibition." (PMID 41437911, 2026). "A major limitation lies in the context dependence of its signalling pathways; Piezo1’s functional output in CAFs can vary fundamentally depending on tumour type and microenvironmental composition, raising questions about its suitability as a universal therapeutic target." (PMID 41437911, 2026). "Within the complex network of the TME, Piezo1 regulates inflammatory responses, angiogenesis, and immune cell recruitment through endothelial cell mechanosensing, thereby creating a microenvironment that promotes tumour immune evasion." (PMID 41437911, 2026). "Role of ECM stiffness and Piezo1 in modulating tumor progression and microenvironment." (PMID 41607548, 2026). "Therefore, combining anti-PD-1 antibodies with Piezo1 inhibitors (e.g. GsMTx4) significantly enhances T cell infiltration and tumour suppression." (PMID 41437911, 2026). "Our findings suggest that elevated PIEZO1 expression may contribute to tumor aggressiveness and progression." (PMID 40724850, 2025). "The 0.5, 1, and 2 h treatment intervals showed larger tumor size compared to the 0 and 4 h treatments, so it is possible that an unknown mechanism following treatment in some tumors promoted Piezo1 downregulation." (PMID 39976192, 2025).
tumor (continued). "Therefore, Piezo1 is not only an important regulator in tumor biology but also a potential novel target for anti-tumor therapy." (PMID 41195420, 2025). "Thus, Piezo1 possesses dual “pro-tumor” and “immune-regulatory” attributes, forming a critical hub where mechanical signaling, tumor biology, and the immune milieu intersect." (PMID 40821847, 2025). "PIEZO1 is upregulated in ovarian cancer tissues, promoting tumor growth and metastasis." (PMID 40977743, 2025). "Piezo1 in Stromal Cells: Stromal cells, particularly fibroblasts and smooth muscle cells, serve as structural support within tissues and play critical roles in tumor progression and immune responses." (PMID 40821847, 2025). "While Piezo1 promotes processes such as epithelial remodeling and tumor invasion via pathways like RhoA/ROCK and YAP/TAZ, Piezo2 is more associated with sensory neuron activity, immune modulation, and tumor aggressiveness." (PMID 42211053, 2025). "As tumor cells undergo changes in their mechanical properties, these alterations may lead to aberrant activation of Piezo1, which in turn promotes tumor cell proliferation, metastasis, and drug resistance." (PMID 40821847, 2025). "Similarly, CAR T cells produced by accelerated 3-day manufacturing preserved higher Piezo1 activity and metabolic vigor than conventional 9-day products, translating into superior tumor clearance." (PMID 41282104, 2025). "Tracking CTC dissemination in vivo, particularly in tumour regions subject to mechanical compression or in proximity to blood vessels, could offer further insight into the relevance of PIEZO1-mediated signalling under physiologic conditions." (PMID 40890143, 2025). "The synergistic potential between Piezo1 inhibition and integrin‐targeted agents could address tumor microenvironment‐driven resistance mechanisms, particularly in malignancies where ECM stiffness and mechanosensitive pathways drive progression." (PMID 40667648, 2025). "Piezo1, a mechanosensitive ion channel, plays a pivotal and multifaceted role in tumor progression, immune evasion, and therapeutic resistance by transducing extracellular mechanical stimuli—such as matrix stiffness and fluid shear stress—into intracellular calcium influx." (PMID 40821847, 2025). "ccRCCs with increasing tumor grade more frequently had PIEZO1 high- than PIEZO1 low-expression." (PMID 40724850, 2025). "Piezo1 was mostly diffuse in the cytoplasm in control tumor cells with no sign of association with peripheral adhesions." (PMID 40060768, 2025). "Nonetheless, recent transcriptomic studies have suggested that PIEZO1 mRNA expression may serve as a potential prognostic biomarker in this tumor type." (PMID 40724850, 2025). "By converting mechanical signals from the TME (such as matrix stiffness, fluid shear stress, and intercellular tension) into Ca2+ influx, Piezo1 activates multiple downstream signaling pathways, regulating tumor cell proliferation, migration, invasion, and immune evasion." (PMID 41195420, 2025). "Future research should focus on clarifying whether PIEZO1 operates through shared signaling pathways across tumor types or plays context-specific roles in different cancers." (PMID 40724850, 2025). "In early stage ccRCC, the prognostic impact of PIEZO1 expression may be attenuated by the predominance of other clinical factors such as tumor size, histological grade, and the generally favorable outcome following complete surgical resection." (PMID 40724850, 2025). "The expression of Piezo1 and ITGB1 was also associated with tumor size and number." (PMID 40667648, 2025). "Moreover, Piezo1’s role in regulating the mechanical response of tumor stromal cells and vascular endothelial cells is significant, as its activation can promote angiogenesis and nutrient supply, further supporting continuous tumor growth." (PMID 41195420, 2025).
tumor (continued). "This aligns with previous evidence that links PIEZO1 to mechanotransduction under low-oxygen environments, where it may enhance tumor cell survival and progression." (PMID 40724850, 2025). "Moreover, their results demonstrated that PIEZO1 expression correlates with matrix stiffness and calcium influx and functionally contributes to tumor progression." (PMID 40724850, 2025). "Thus, results demonstrated that ultrasound treatment promoted Piezo1 expression and its localization to the mature adhesions at the cell periphery in tumor cells." (PMID 40060768, 2025). "Moreover, it is plausible that PIEZO1 contributes to the adaptation of ccRCC cells to mechanical and metabolic stress within the tumor microenvironment, particularly under hypoxic conditions typical for renal tumors." (PMID 40724850, 2025). "Interestingly, YAP plays an essential role in this anti‐tumor regulation of Piezo1, contrary to its known role in promoting cancer progression." (PMID 40583158, 2025). "Notably, PIEZO1 expression was more pronounced in peritumoral tubular epithelium than in the tumor tissue itself." (PMID 40724850, 2025). "In addition to promoting the tumor cells’ own adaptability, Piezo1 also influences cancer progression by regulating the tumor immune microenvironment." (PMID 41195420, 2025). "He found that activation of Piezo1 in tumor cells led to nuclear accumulation of YAP." (PMID 41457305, 2025). "Hence, we examined if ultrasound treatment (33 kHz) promoted Piezo1 translocation to the peripheral adhesions in the tumor cells' plasma membrane." (PMID 40060768, 2025). "We thus hypothesize that PIEZO1 may modulate the malignant behavior of tumor cells via ion transporters." (PMID 40977743, 2025). "Further studies are needed to determine whether PIEZO1 silencing in KICH represents a passive bystander effect or an active tumor-suppressive adaptation." (PMID 40977743, 2025). "Thirdly, PIEZO1 may drive tumor progression through ECM-receptor interactions, cell migration, and ion transport." (PMID 40977743, 2025). "The elevated PIEZO1 expression in Tregs may promote tumor immune escape and progression by modulating Treg function within the tumor microenvironment." (PMID 40977743, 2025). "Tumor ball formation was blocked in GBM stem cells after Piezo1 knockdown." (PMID 40061015, 2025). "Furthermore, Piezo1 expression correlates with distinct tumor immune phenotypes, such as “cold tumors,” and with responses to immunotherapy, making it a promising predictive biomarker for treatment efficacy." (PMID 40821847, 2025). "As a pivotal mechanosensitive ion channel, Piezo1 plays a central role in tumor progression." (PMID 40821847, 2025). "Additionally, PIEZO1 depletion inhibited ALDH1B1 expression in tumor cells confined within lung capillaries." (PMID 41390768, 2025). "Additionally, blockade of Piezo1 in T cells has been shown to significantly enhance their cytotoxic activity against tumor cells." (PMID 40667648, 2025). "These tumor-specific expression patterns suggest that PIEZO1 may exert context-dependent functions across different cancer types, potentially reflecting diverse regulatory mechanisms and biological roles." (PMID 40724850, 2025). "Although Piezo1 has been identified as a key sensor and effector in tumor angiogenesis, whether it acts in conjunction with tumor-type-specific cofactors or exhibits dose- and time-dependent functional polarity remains unclear." (PMID 40821847, 2025). "Further functional studies are needed to clarify whether PIEZO1 exerts a pro-tumorigenic or potentially dual role in ccRCC, depending on tumor stage, differentiation, or microenvironmental pressure." (PMID 40724850, 2025). "PIEZO1 positively correlated with tumor microenvironment scores and immune checkpoints." (PMID 40977743, 2025). "In NK cells, Piezo1 activation enhances cytotoxicity and tumor infiltration capacity." (PMID 40821847, 2025). "This highlights Piezo1 as the primary mediator of ES-driven tumor suppression." (PMID 39940798, 2025).